TOX3 (TOX high mobility group box family member 3)
Diseases named in the same sentence as TOX3 in open-access papers (continued):
Sharing a sentence is not in itself a finding about the gene and the disease.
Alzheimer disease (1 paper, 2025). A progressive, neurodegenerative disease characterized by loss of function and death of nerve cells in several areas of the brain leading to loss of cognitive function such as memory and language. "Our analysis identified several transcription factors with no previous association with Alzheimer's disease in astrocytes, including TOX3, MKX, ZBTB18, and ZNF382." (PMID 40656638, 2025).
amenorrhea (1 paper, 2019). The absence of menses in a woman who has achieved reproductive age. "TheTHADA rs13429458 and TOX3 rs4784165 variants were significantly associated with the combined oligo/amenorrhea (OA) and polycystic ovarian morphology subgroups while the HMGA2 rs2272046variant was significantly associated with the combined HA and OA subgroup." (PMID 31902981, 2019).
Ataxia (1 paper, 2026). Ataxia refers to impaired coordination of voluntary muscle movement. "Tox3-deficient mice display severe ataxia and cerebellar hypoplasia, driven by depletion of GNPs, diminished Atoh1 expression, and impaired primary cilia." (PMID 41849381, 2026).
bone metastasis (1 paper, 2019). Transfer of a neoplasm from its primary site to bones. "It has been also suggested that an amplified expression of TOX3 can lead to bone metastasis." (PMID 31528229, 2019).
colorectal tumors (1 paper, 2023). "Consistently, the expressions of genes related to cancer stem-like traits were increased in the colorectal tumors of OXA treatment mice, compared to NS treatment mice, including TOX3, WDR5, and ABCG2." (PMID 37708089, 2023).
hyperandrogenism (1 paper, 2024). Excessive secretion of androgens from the adrenal glands or gonads. "Similarly, SNPs within YAP1, TOX3 and IRF1/RAD50 were only significant in the lean group, and have previous association with ovulatory dysfunction, hyperandrogenism and increased testosterone levels respectively." (PMID 38408933, 2024).
Joubert syndrome (1 paper, 2025). Joubert syndrome (JS) is characterized by congenital malformation of the brainstem and agenesis or hypoplasia of the cerebellar vermis leading to an abnormal respiratory pattern, nystagmus, hypotonia, ataxia, and delay in achieving motor milestones. "Of particular interest, they affected neuronal genes, including Ahi1 (implicated in Joubert syndrome), Tox3 (a calcium-dependent transactivator), and Htr5a (a serotonin receptor), all of which are implicated in neuronal function and psychiatric disorders (57, –59)." (PMID 40802685, 2025).
medulloblastoma (1 paper, 2026). A malignant, invasive embryonal neoplasm arising from the cerebellum. "TOX3 is also highly expressed in subsets of medulloblastoma, and its deletion reduces cerebellar neoplasia and prolongs survival in a mouse model." (PMID 41849381, 2026).
metastatic tumor (1 paper, 2023). "Furthermore, in line with the ABCG2 expression level, TOX3 showed a high expression in the recurrent or metastatic tumor tissues of patients with CRC." (PMID 37708089, 2023).
Miscarriage (1 paper, 2019). A pregnancy that ends at a stage in which the fetus is incapable of surviving on its own, defined as the spontaneous loss of a fetus before the 22th week of pregnancy. "The association between TOX3 rs3803662 C>T polymorphism and miscarriages and other parameters, such as the number of abortions and the age at which miscarriages occurred, was not significant." (PMID 31454102, 2019).
orofacial cleft (1 paper, 2019). A disorder of facial skeleton that is characterized by cleft lip and/or cleft palate that result in feeding, speech and hearing problems caused by failures during development. "Currently, it has never been reported that the TOX3 was susceptible to nonsyndromic orofacial cleft occurrence." (PMID 30924295, 2019).
osteoarthritis (1 paper, 2023). A noninflammatory degenerative joint disease occurring chiefly in older persons, characterized by degeneration of the articular cartilage, hypertrophy of bone at the margins and changes in the synovial membrane. "The distinct immune profiles and involvement in fat metabolism pathways associated with TOX3 expression suggest its significance in Osteoarthritis pathogenesis." (PMID 38020130, 2023). "In conclusion, our study presents a comprehensive analysis identifying TOX3 as a potential feature gene in Osteoarthritis." (PMID 38020130, 2023). "The osteoarthritis samples were categorized into two groups, namely a high expression group and a low expression group, based on the median levels of TOX3 expression." (PMID 38020130, 2023). "Validation of TOX3 expression was confirmed using an external dataset (GSE29746), revealing a notable increase in Osteoarthritis samples." (PMID 38020130, 2023).
pancreatic cancer (1 paper, 2024). "In an effort to identify crucial biomarkers for pancreatic cancer prognosis, a study discovered a total of four genes, ACSL5, SLC44A4, LOX, and TOX3, showing correlation with PFS as indicated by qPCR and immunohistochemical staining." (PMID 39108264, 2024).
restless legs syndrome (1 paper, 2016). A condition that occurs while resting or lying in bed; it is characterized by an irresistible urgency to move the legs to obtain relief from a strange and uncomfortable sensation in the legs. "Genetic variants in the region of TOX3 have been previously associated with restless legs syndrome in a GWAS38." (PMID 26955885, 2016). "Although the chronotype-associated variant (rs12927162) is not in linkage disequilibrium with the lead restless legs syndrome variant (rs3104767; r2<0.001 in 1KG CEU population), it does suggest that TOX3 may have a broader role in basic sleep/circadian physiology." (PMID 26955885, 2016).
triple-negative breast carcinoma (1 paper, 2015). An invasive breast carcinoma which is negative for expression of estrogen receptor (ER), progesterone receptor (PR), and human epidermal growth factor receptor 2 (HER2). "This might also explain the association of the TOX3 risk allele with triple negative breast cancer." (PMID 25632947, 2015).
cancer (28 papers, 2009 to 2025). A tumor composed of atypical neoplastic, often pleomorphic cells that invade other tissues. "Although TOX3 has been implicated in various types of cancer, there is currently a scarcity of in vivo and in vitro experimental studies investigating the association between TOX3 and OA." (PMID 38020130, 2023). "The TOX3 SNP causative of increased cancer risk is located 18 kb upstream of the TOX3 transcription start site." (PMID 25632947, 2015). "The apparent paradox whereby low TOX3 is associated with cancer risk and high expression is associated with poor outcome is discussed in relation to TOX3 expression in a subset of normal mammary epithelial cells." (PMID 25632947, 2015). "Since TOX3 overexpression is associated with poorer outcome in patients with LumB cancer, we also sought to identify genes whose expression would be influenced by expression of this nuclear protein." (PMID 25632947, 2015). "It is worth mentioning that TOX3 has been linked to studies on cancer." (PMID 38020130, 2023). "The validation results demonstrated that the TOX3 expression level was markedly upregulated in cancer tissues versus adjacent normal liver tissues." (PMID 38463397, 2024). "Compared with the control, CRC spheroids derived from the cancer cells with TOX3 knockdown or overexpression showed decreased or elevated expression of ABCG2 and stem-like traits-associated protein markers." (PMID 37708089, 2023). "Our results showed that WDR5 knockdown or inactivity reversed the down-regulated sensitivity of CRC cells to oxaliplatin caused by TOX3 overexpression, while WDR5 overexpression desensitized cancer cells to oxaliplatin based on TOX3 knockdown." (PMID 37708089, 2023). "TOX high mobility group box family member 3-like (TOX3) in the spleen has been shown to inhibit the proliferation and migration of cancer cells by transcriptional regulation of SNAI1 and SNAI2 to prevent disruption of the epithelial cell layer." (PMID 34135900, 2021). "TOX3 also upregulates a set of ER target genes that are involved in the cell cycle, cancer progression, and metastasis." (PMID 33716953, 2020). "This identified 160 significant non-coding elements, including the TERT promoter, a well-known non-coding driver element, as well as elements associated with known cancer genes and regulatory genes (e.g., PAX5, TOX3, PCF11, MAPRE3)." (PMID 29354286, 2018). "Bisulfite sequencing of four CpG islands in the TOX3 promoter showed a clear difference between luminal and basal-like cancer cell lines." (PMID 27806084, 2016). "These variants were found in genes associated with cancers (ANKRD35, DNAH9, MAGEC1, TOX3) or participating in cancer-related signaling pathways (THSD1, MORN2, PTCRA)." (PMID 26822197, 2016). "TOX was almost exclusively methylated in breast (43%) than lung (5%) cancer, whereas TOX3 was frequently methylated in lung (58%) than breast (30%) tumors." (PMID 22496870, 2012). "However, hitherto, the published work shows contradictory results relating to its impact on tumorigenesis, suggesting that more careful dissections are required for TOX3 in different cancer types and different stages of the same cancer type." (PMID 37708089, 2023). "Since TOX3 has been reported to be a survival factor for cancer cells in the nervous system, it was further examined whether TOX3 protects granulosa cells from apoptosis." (PMID 33716953, 2020). "5-Aza-2’-deoxycytidine treatment of a basal-like cancer cell line increased expression of TOX3." (PMID 27806084, 2016). "Using a threshold of >10% of stained epithelial cells, ~15% of the cancers expressed TOX3." (PMID 25632947, 2015). "Expression of TOX3 may be involved in the resistance to endocrine therapy reported to occur in some LumB cancers." (PMID 25632947, 2015). "In contrast, basal subtype cancers rarely expressed TOX3, consistent with a previous report." (PMID 25632947, 2015).
cancer (continued). "In silico predictions indicated that a metastatic suppressor gene such as KLF17 and two cellular protein, RBM10 and TOX3 which are involved in proliferation and apoptosis of cancer cells could be the actors influencing the outcome of BRAF inhibitor therapy." (PMID 25437182, 2014). "The synergistic anchoring of TOX3 with WDR5 at the promoter of ABCG2 causes the enrichment of histone H3K4 tri-methylation, thereby further promoting ABCG2 transcription and expression and subsequent cancer stem-like traits expansion and drug sensitivity deregulation." (PMID 37708089, 2023). "Thus, whether TOX3 plays dual and opposing roles in cancer initiation and progression remains to be determined." (PMID 25632947, 2015). "To explore the role of TOX3/ABCG2 signaling axis in CRC, we firstly investigated the function of TOX3 itself in cancer development." (PMID 37708089, 2023). "It is interesting, in this regard, that TOX3 downregulation has been reported to facilitate epithelial-to-mesenchymal transition by repression of SNAI1 and SNAI2 in cancer cells." (PMID 36794750, 2023). "Given the results above, we assumed that WDR5 tri-methylates H3K4 at ABCG2 promoter to further recruit TOX3 resulting in the up-regulation of ABCG2 transcription and ultimately in the development of cancer stem-like traits and drug resistance." (PMID 37708089, 2023). "TOX3 overexpression reversed the inhibition at the transcription of ABCG2, the expression of cancer stem-like traits-related genes, clonogenicity, spheroid formation, and CSC frequency induced by WDR5 knockdown, and vice versa." (PMID 37708089, 2023). "Furthermore, given the effects of TOX3 on neuronal cells, rs3803662 increasing the survival of diffuse-type gastric cancer in a dominant model might be attribute to inhabit a host cell into a tumor cell or cancer cells multiply rapidly by unknown mechanisms." (PMID 24069142, 2013). "Extension of these assays to TOX, TOX3, and TOX4 genes that share similar genomic structure and protein homology with TOX2 revealed distinct methylation profiles by smoking status, histology, and cancer type." (PMID 22496870, 2012).
tumor (26 papers, 2007 to 2026). "Paradoxically, while some studies associate TOX3 with tumor suppression, elevated TOX3 expression has also been linked to poor prognosis and an increased risk of bone metastasis, particularly in ER-positive breast cancer patients." (PMID 41596432, 2026). "During early tumorigenesis, TOX3 is expressed in breast epithelial progenitor cells and has been linked to tumor initiation." (PMID 41596432, 2026). "The SNP rs3803662:C > T is the most common genetic variant of TOX3, linked to BC and its T allele, which influences BC prognosis, advanced tumor stages, poor survival, and luminal molecular subtypes or ER-positive expression." (PMID 39390525, 2024). "This indicates that both alleles of TOX3 are potentially inactivated in this tumour, one by LOH and the other by point mutation." (PMID 24069272, 2013). "We screened all seven exons of TOX3 for mutations in one set of 46 primary tumour samples using Sanger sequencing." (PMID 24069272, 2013). "In ER positive tumours, TOX3 expression decreased significantly with the number of risk alleles (p = 0.002)." (PMID 23270421, 2012). "An association of the risk allele of rs3803662 with lower TOX3 expression was confirmed in oestrogen receptor (ER) positive tumours." (PMID 23270421, 2012). "In our study, the allele-dependent decrease of TOX3 or LOC643714 mRNA level was only observed in ER positive tumours." (PMID 23270421, 2012). "The inverse association between TOX3 expression and disease risk has led to the suggestion that TOX3 may act as a tumor suppressor." (PMID 25632947, 2015). "Also, we found that four out of five tumours with TOX3 mutations, for which we had clinical information, were of Luminal A type." (PMID 24069272, 2013). "The present study examined TOX3 expression in tumor and adjacent normal liver tissues from 72 HCC patients who underwent selected hepatectomy at our center." (PMID 38463397, 2024). "LDA assay showed TOX3 overexpression increased stem-like traits of the tumor cells and promoted tumor growth, but OICR9429 treatment reversed this promotion." (PMID 37708089, 2023). "Recent studies have demonstrated that the mRNA expression of TOX2 and TOX3 is significantly elevated in tumor tissue from individuals with sCRC, suggesting a potential role for these molecules in the development and progression of the disease." (PMID 37835436, 2023). "We also found that mRNA levels of TOX2 and TOX3 were significantly higher in CRC tumor tissues, suggesting their potential roles in CRC development and/or progression." (PMID 32393998, 2020). "TOX3 has been newly identified as a ccRCC suppressor gene as it inhibited tumor cell migration and invasion by repressing the SNAIL members SNAI1 and SNAI2 at the transcriptional level." (PMID 32789468, 2020). "When the cases were stratified according to tumor features, it was observed that the SNPs in FGFR2 and TOX3 were associated with the disease." (PMID 26770289, 2016). "Given our results of ligand-independent estrogen target gene upregulation by TOX3 in tumor cells, it is possible that TOX3 also contributes to the relative insensitivity of these progenitors to estrogen deprivation." (PMID 25632947, 2015). "On the other hand, an association between TOX3 overexpression in tumours and lower BRCA1 expression and tumour aggressiveness has been reported recently." (PMID 24069272, 2013). "Tumours of patients who were lymph node positive when diagnosed, had significantly higher TOX3 and LOC643714 mRNA levels than tumours of lymph node negative patients (p < 0.001 and p = 0.04, respectively)." (PMID 23270421, 2012).
tumor (continued). "Patients with ER positive tumours and high levels of TOX3 mRNA had shorter overall- and distant metastasis free-survival (p = 0.017 and p = 0.021), an effect mostly attributable to patients with luminal B tumours." (PMID 23270421, 2012). "Patients with tumours that express high TOX3 mRNA had shorter DMFS and OS (p = 0.015 and p = 0.022, respectively)." (PMID 23270421, 2012). "Tumours with high expression of Ki67 had significantly lower TOX3 and LOC643714 mRNA levels than tumours with low expression of Ki67 (p = 0.026 and p < 0.001, respectively)." (PMID 23270421, 2012). "Stratifying POSH cases by tumour characteristics identified SNPs in FGFR2 and TOX3 associated with ER-positive disease and SNPs in ATM associated with ER-negative disease." (PMID 19094228, 2008). "Moreover, according to the results of this study, the inhibitory effect of downregulating Tox3 expression on the proliferative capacity of HCC tumor cells was dramatically greater than that on human normal hepatocytes." (PMID 38463397, 2024). "Pathway enrichment analysis revealed that the regulation of TOX3 could significantly affect signaling pathways related to tumor growth and metastasis, such as the MAPK pathway and the EMT." (PMID 38463397, 2024). "The results of high‐throughput RNA sequencing showed that the regulatory effect of TOX3 on the malignant biological behavior of HCC cells involved mainly focused on signaling pathways related to tumor growth and metastasis, such as the KRAS, MAPK, and EMT pathways." (PMID 38463397, 2024). "Furthermore, the primary CRC cells were obtained from the formed xenograft tumor masses, and the same results were shown in the ability of spheroid formation and colony formation as in vitro upon TOX3 knockdown and/or ABCG2 overexpression." (PMID 37708089, 2023). "We speculated that as more factors may be involved in TOX3-related mechanisms of tumor progression, more studies are needed to clarify the relationship between TOX3 expression and tumor progression." (PMID 29285217, 2017). "One of these studies also links the lower expression of TOX3 with tumour grade and poorer outcome." (PMID 24069272, 2013). "Recent reports have provided data that both support and reject the tumour suppressor role of TOX3." (PMID 24069272, 2013). "It is possible that TOX3 might play a complex role in promoting tumour development or protecting against it in a subtype-specific manner." (PMID 24069272, 2013). "In these tumours, TOX3 would appear to be a tumour suppressor." (PMID 23270421, 2012). "Additionally, the proliferation capacity of the nude mice in the subcutaneous tumor model was substantially enhanced after TOX3 was overexpressed (OE‐TOX3), and the size and weight of the subcutaneous tumors increased significantly after TOX3 was overexpressed." (PMID 38463397, 2024). "However, it is mentioned that TOX3 promoted tumor cell proliferation." (PMID 33716953, 2020). "To investigate whether the mutational status of these tumours was associated with altered levels of expression of TOX3, we compared mutated vs non-mutated." (PMID 24069272, 2013). "We hypothesised that TOX3 could be a candidate tumour suppressor gene in 16q." (PMID 24069272, 2013). "Furthermore, higher TOX3 mRNA was observed in patients with luminal B tumours with metastasis (p = 0.056, data not shown) but more tumours are necessary to observe a significant association of metastasis to bone as has been reported with high TOX3 expression." (PMID 23270421, 2012). "However, a different scenario has been described in neuronal cells that potentially may explain the effect of high TOX3 mRNA in ER positive tumours which we ascribe to luminal B tumours." (PMID 23270421, 2012). "Therefore, the correlation of FOXA1 expression with luminal A tumours could explain lower expression of TOX3 in our study and poorer survival of carriers of the rs3803662 risk allele and luminal A tumours." (PMID 23270421, 2012).